MIR125B1 (microRNA 125b-1)
Synonyms: hsa-mir-125b-1; MIRN125B1; mir-125b-1
Gene: MicroRNA gene on chromosome 11 (122,099,757 to 122,099,844, reverse strand). Ensembl gene ENSG00000207971.
Gene Ontology:
Biological process: miRNA-mediated post-transcriptional gene silencing
Cellular component: RISC complex
Homologues: Orthologues: chimpanzee ptr-mir-125b-1 (100% identical), macaque mml-mir-125b-1 (99% identical), dog MIR125B1 (98% identical), rabbit MIR125B1 (98% identical), rat Mir125b1 (97% identical), pig ssc-mir-125b-1 (90% identical), tropical clawed frog xtr-mir-125b-1 (88% identical), mouse Mir125b-1 (86% identical), guinea pig MIR125B1 (84% identical), zebrafish mir125b-1 (76% identical), zebrafish mir125b-2 (72% identical). Paralogues in human: MIR125B2 (65% identical), MIR125A (60% identical), MIR10A (40% identical), MIR10B (40% identical), MIR100 (39% identical), MIR99A (39% identical), MIR99B (35% identical).